FCRL4 (Fc receptor like 4)
Diseases named in the same sentence as FCRL4 in open-access papers (continued):
Sharing a sentence is not in itself a finding about the gene and the disease.
marginal zone lymphoma (2 papers, 2016 to 2019). A usually indolent mature B-cell lymphoma, arising from the marginal zone of lymphoid tissues. "Furthermore, FCRL4 was selectively identified in nodal and extranodal marginal zone lymphomas (MZL), and is considered a positive marker for MZL." (PMID 27446638, 2016).
Autoimmunity (1 paper, 2025). The occurrence of an immune reaction against the organism's own cells or tissues. "TNFSF11 (RANKL) was also found in FCRL4-expressing B cells in the context of autoimmunity, in the population defined as pro-inflammatory and probably contributing to RA pathogenesis." (PMID 40990023, 2025).
colorectal carcinoma (1 paper, 2025). A malignant epithelial neoplasm that arises from the colon or rectum and invades through the muscularis mucosa into the submucosa. "Previously, Bexh, along with exhausted T and NK cells, were found in colorectal carcinoma (CRC) samples, where high expression of FCRL4, as well as other exhaustion genes, was significantly associated with worse prognosis independently of tumor’s molecular subtype." (PMID 40990023, 2025).
dengue (1 paper, 2019). "Even though percentages of FcRL4+ B cells were low in naïve B cells of dengue positive patients, we did not evaluate other subsets of atypical B cells such as FcRL5+, CD11c+T-bet+, T-bethiCD85jhi, or CD21−/loCD27− B cells, which might affect our results." (PMID 31736948, 2019).
hyperthyroidism (1 paper, 2024). Overactivity of the thyroid gland resulting in overproduction of thyroid hormone and increased metabolic rate. "On the basis of our results, we can assume that the increased expression of the FCRL4 gene in GD patients is rather a result than a cause of GD, with a leading role of this phenomenon being hyperthyroidism." (PMID 39274506, 2024). "Among the three subtypes of FCRLs, the only variable associated with hyperthyroidism was FCRL4 mRNA expression (above and below)." (PMID 39274506, 2024). "Hyperthyroidism can be considered as a form of inflammation caused by the systemic effects of increased thyroid hormones and, in this sense, can lead to an increase in FCRL4 B-cells in peripheral blood." (PMID 39274506, 2024). "In turn, FCRL4 mRNA expression was higher in patients with hyperthyroidism (subclinical + overt) than in euthyroid patients (2.509 vs. 0.995, p = 0.001 when the whole group of individuals was considered; 2.509 vs. 1.073, p = 0.004 when GO + GD was considered)." (PMID 39274506, 2024). "Regarding the other potential mechanism, our research has shown a completely new relationship between FCRL4 mRNA expression and hyperthyroidism." (PMID 39274506, 2024). "Instead, FCRL4 mRNA expression was higher in patients with hyperthyroidism (subclinical + overt) than in euthyroid patients (2.509 vs. 0.995, p = 0.001) when the whole group of individuals was considered (left) as well as when only GO + GD was considered (2.509 vs. 1.073, p = 0.004) (right)." (PMID 39274506, 2024). "That is why it can be hypothesized that hyperthyroidism could be a factor favoring the presence of B-cells, among other B-cells, expressing FCRL4 in peripheral blood." (PMID 39274506, 2024). "In conclusion, our findings indicate that FCRL3 and FCRL4 expression levels are significantly increased in patients with GD and that this phenomenon is associated with hyperthyroidism but not with thyroid autoimmunity." (PMID 39274506, 2024).
IgA nephropathy (1 paper, 2024). "There is evidence indicating significant alterations in the level of H3K4me3 of fc receptor like 4 (FCRL4) and galactokinase 2 (GALK2) in peripheral blood mononuclear cells of IgA nephropathy patients." (PMID 39595187, 2024).
kidney carcinoma (1 paper, 2025). Primary or metastatic malignant neoplasm involving the kidney. "The cancer genome atlas (TCGA) was used to analyze possible association between increased presence of FCRL4 among Bmem cells and survival of lung adenocarcinoma and kidney carcinoma (KIRC) patients." (PMID 40990023, 2025). "According to The Cancer Genome Atlas (TCGA) data, LUAD tumor progression was accompanied by a decrease in FCRL4 levels, whereas renal carcinoma showed a substantial increase in FCRL4 expression as the tumor progressed from stage I to stage IV." (PMID 40990023, 2025).
lung adenocarcinoma (1 paper, 2025). A carcinoma that arises from the lung and is characterized by the presence of malignant glandular epithelial cells. "However, we found upregulation of two inhibitory receptors - FCRL4 and PDCD1 (PD-1) - in IgA+ B cells in lung adenocarcinoma (LUAD)." (PMID 40990023, 2025).
multiple sclerosis (1 paper, 2022). A progressive autoimmune disorder affecting the central nervous system resulting in demyelination. "Separately, de novo EBV infection led to the development of CXCR3+/CD11c+/FCRL4+ B cells within days, providing evidence for possible T cell-independent origins of a recently described EBV-associated neuroinvasive CXCR3+ B cell subset in patients with multiple sclerosis." (PMID 36248899, 2022).
Sjögren’s syndrome (1 paper, 2020). "In primary Sjögren’s syndrome (pSS), FcRL4+ B cells are present in inflamed salivary gland tissue, within or in close proximity to ductal epithelium." (PMID 32201227, 2020).
tumor (17 papers, 2020 to 2026). "Single-cell transcriptomic studies have further identified tumor-associated atypical B cells marked by FCRL4 expression, enriched for MHC-II and CD4+ T-cell interactions, and precursors of antibody-secreting cells." (PMID 41364090, 2026). "Taken together, our analysis suggests that FCRL4+FCRL5+ B cells are associated with anti-tumor activity and a positive response to combined therapy." (PMID 36869384, 2023). "Studies have shown that the spatial distribution and differentiation state of tumor-associated B cells (such as FCRL4+ B cells) and CD8+ T cells in NPC may impact patient prognosis and the effectiveness of immunotherapy." (PMID 41399390, 2026). "In one of our previous studies, we found that CD20+FCRL4+ B cells play a crucial role in the anti-tumor immune response in NPC26." (PMID 41399390, 2026). "We note that both of these modes of action can potentially limit antitumor immune response, adding to the protumorigenic role of FCRL4+ tumor-infiltrating memory B cells." (PMID 40990023, 2025). "FCRL4 upregulation appears to be a tumor-specific feature, as according to the scRNA-seq data from the normal lung tissue from the same dataset, FCRL4 is not expressed by any cluster." (PMID 40990023, 2025). "The CellphoneDB analysis identified significant crosstalk among various cell types related to immunoregulation, including TREG, CD8 TDYS, FCRL4+ MBCs, C1Q+ Mφ, and tumor cells, which was more prominent in RR than ND TFHL." (PMID 38012392, 2024). "In KIRC samples, FCRL4 expression was low both in tumor and matched normal tissue samples." (PMID 40990023, 2025). "Also, in LUAD samples, expression of FCRL4 was significantly higher in tumor samples, compared to the matched normal tissue." (PMID 40990023, 2025). "In addition to IPA, we could identify specific patterns of gene expression associated with CD11c+ B cells, B cell differentiation, and tumor suppression in FcRL4+ B cells." (PMID 32201227, 2020). "The data suggest that in the TME of immunotherapy responders, FCRL4+ FCRL5+ B cells are driven by IFNα, TNF, and IL27 signals, and Tfhs are activated by these B cells to enhance anti-tumor immunity through secreting IL21." (PMID 36869384, 2023). "In sample-level scRNA-Seq correlations of tumours, FRC-like fibroblasts positively correlated with various B-cell subsets [including cycling B-cells, FCRL4 + B-cells and germinal centre (GC) B-cells], plasma cells, KIT + NK-cells, with high correlation with IgM expressing B/plasma cells." (PMID 39757146, 2025). "Therefore, these four tumor antigens (NLCR4, LCP2, TMEM229B, FCRL4) were considered as potential candidates for ESCC mRNA vaccine with immune activation and can be processed and presented by APCs to induce an immune response." (PMID 35734437, 2022). "Since the presence of tumor-infiltrating B cells was usually correlated to better overall survival and treatment outcomes, we selected several representative B-cell signatures (CD79A, MS4A1, IGHD, and FCRL4) and examined their prognostic values in NPC patients." (PMID 33750785, 2021).
cancer (5 papers, 2015 to 2025). A tumor composed of atypical neoplastic, often pleomorphic cells that invade other tissues. "Briefly, we examined the expression changes of proliferation and apoptosis markers before and after FCRL4 knock‐down, results showed that inhibition of FCRL4 can suppress cancer cell proliferation and promote cell apoptosis." (PMID 39580787, 2024). "Here we selected the top gene with highest Hazzard Ratio, FCRL4, to test the regulatory potential in key biological processes of cancer cells." (PMID 39580787, 2024). "Results showed that inhibition of FCRL4 can repress cancer cell invasion and metastasis." (PMID 39580787, 2024). "Additionally, would healing assay and colony formation assays revealed the anti‐cancer role of knockdown FCRL4." (PMID 39580787, 2024). "Furthermore, the results of Tunel experiments also demonstrated that knocking down FCRL4 could enhance the apoptotic activity of cancer cells." (PMID 39580787, 2024). "As a result, seven DEGs correlated with more than 10 TR-DDR genes (r>0.3) in at least 10 cancers were regarded as candidate genes, including COL2A1 (the R ranged from 0.39 to 0.60), MAGEA4 (0.24–0.62), FCRL4 (0.33–0.62), ZIC1 (0.24–0.33), LCN15 (0.20–0.41), PRSS3 (0.24–0.35), CSAG1 (0.31–0.38)." (PMID 36081518, 2022).
infection (3 papers, 2016 to 2022). The state of being infected such as from the introduction of a foreign agent such as serum, vaccine, antigenic substance or organism. "In single cells gated from two biological donors, the average frequency of CD19+/CXCR3+/CD11c-/+/FCRL4+ gated cells was 38.6 ± 15.7% at day 8 post-infection compared to 9.8 ± 3.2% of cells prior to infection (n = 2 LCLs, two-tailed Welch’s t-test p = 0.224)." (PMID 36248899, 2022). "After the first several days of infection, the percentage of CD19+/CXCR3+/CD11c+ that also expressed FCRL4 (an inhibitory receptor and EBV-induced host biomarker) progressively increased (third column)." (PMID 36248899, 2022). "In the de novo infection context, we found that EBV increases CXCR3 (as well as CD11c and FCRL4) expression on peripheral B cells." (PMID 36248899, 2022). "Moreover, EBV+ CD19+/CXCR3+/CD11c+/FCRL4+ cells and parental CD19+ populations proliferated to a similar extent in response to infection." (PMID 36248899, 2022).
FCRL4 also shares sentences with these, for which no sentence is quoted: chronic gastritis (2 papers); immune disorders (2); viral infections (2); gastric lymphoma (1); Hashimoto thyroiditis (1); heart failure (1); hepatitis B (1); hyperplasia (1); Immunodeficiency (1); infectious disease (1); membranous nephropathy (1); multiple myeloma (1); nasopharyngeal carcinoma (1); reactive lymphoid hyperplasia (1); scleroderma (1); thyroid (1); thyroid autoimmunity (1); vivax malaria (1).